FOXM1 (forkhead box M1)
Diseases named in the same sentence as FOXM1 in open-access papers (continued):
Sharing a sentence is not in itself a finding about the gene and the disease.
tumor (continued). "Indeed, S2-CP8 cells and HPAF-II cells express β-catenin in the nucleus and cytoplasm, and ~80% of PDAC cases positive for both DKK1 and FOXM1 express β-catenin in the same tumor legions." (PMID 34117362, 2021). "To further test whether the Akt/p-Akt and FOXM1 protein levels changed in the xenograft animal model, we measured those levels in the tumor tissue." (PMID 34768915, 2021). "Moreover, we subcutaneously implanted PC cells with either USP28 single-knockdown or USP28 knockdown with FOXM1 overexpression into nude mice and monitored their tumour growth." (PMID 34584067, 2021). "Our data implied that FOXM1 functioned importantly in promotion of tumor growth." (PMID 33391456, 2021). "Thus, UA effectively potentiates the anti-tumor efficacy of PTX by targeting the Akt/FOXM1 cascade since combination treatment shows significantly more anti-tumor potential than PTX alone both in vitro and in vivo." (PMID 34768915, 2021). "In LSCC, miR-370 exerts a tumour suppressor effect through inhibiting the expression of FoxM1." (PMID 34124974, 2021). "Furthermore, FOXM1 altered maturation of bone marrow-derived dendritic cells, inhibited T cell proliferation and decreased IL-12 p70 in tumor-bearing mice." (PMID 33804240, 2021). "In vivo subcutaneous xenotransplanted tumor model also revealed that knockdown of OTUB1 could suppress in vivo RCC growth via down-regulation of FOXM1-mediated ECT2 expression." (PMID 32257108, 2020). "Disrupting the SATB2/CBP complex significantly inhibited tumor growth by inhibiting FOXM1 expression, indicating that targeting the SATB2/CBP signaling axis may have therapeutic potential to improve GBM treatment." (PMID 33124191, 2020). "We found that Rab1A expression was closely related to FoxM1 expression in tumor tissues, whereas no obvious expression association in normal tissues was observed." (PMID 33214609, 2020). "It has been confirmed that FoxM1 is involved in chemotherapy resistance in a variety of tumours." (PMID 32667745, 2020). "Indeed, inhibition of FOXM1 activity using RNA interference system and chemical compounds displayed reduced tumor growth and invasiveness, as well as increased chemosensitivity." (PMID 32858881, 2020). "Knockdown of TESC as well as FOXM1 inhibited tumor cell proliferation and led to G2/M phase arrest." (PMID 32365487, 2020). "Previous evidence indicated that FoxM1 plays important roles in a variety of biological processes including mitotic G1/S and G2/M phase transition, mitotic spindle integrity, DNA damage repair, angiogenesis and tumour metastasis." (PMID 32667745, 2020). "Next, we examined role of FoxM1 in PTTG3P-regulated tumor cell aggressiveness." (PMID 33298873, 2020). "Elevated FOXM1 protein levels were also observed in FOXO3a-knockdown tumor xenografts." (PMID 31296961, 2020). "FOXM1-deficient macrophages failed to migrate to the lung tissue resulting in reduced tumor-associated inflammation known to promote tumorigenesis." (PMID 32271749, 2020). "Furthermore, CENPF collaborates with FOXM1 to synergistically induce target gene expression and leads to activation of crucial signaling pathways correlated with tumor malignancy." (PMID 33061942, 2020). "We suggest that within a tumor the regulation of FOXM1 may not only be carried out by SETD3 but also through other molecules." (PMID 32042016, 2020). "FOXO3a functions as a typical tumor suppressor, whereas FOXM1 is a potent oncogene." (PMID 31296961, 2020). "Results revealed that Rab1A expression was positively associated with FoxM1 expression in TNM stage III, indicating that Rab1A and FoxM1 might have promoted tumor progression." (PMID 33214609, 2020). "Because DNMT1-mediated methylation downregulated FOXO3a expression, we next tested whether pharmacological inhibition of DNMTs could suppress tumorigenesis and tumor growth by regulating FOXO3a/FOXM1/SOX2 signaling." (PMID 31296961, 2020).
tumor (continued). "These further implied the molecular mechanism of miR-320d for tumor progression may be through regulating FoxM1 in GCA tumors." (PMID 32551039, 2020). "The tumour suppressor FOXO3 can antagonise the oncogenic activity of FOXM1 in a number of ways." (PMID 32372224, 2020). "High expression levels of FOXM1 was positively correlated with large tumor size, poor differentiation degree, deep invasion, and low survival rate and might serve as an independent prognostic indicator for determining prognosis of ESCC patients." (PMID 32047721, 2020). "Moreover, in vivo data revealed that FOXM1 depletion inhibited tumor growth and resulted in lightened tumor weight." (PMID 32513952, 2020). "FOXM1 has been identified as a master regulator of tumor invasion and metastasis." (PMID 33292277, 2020). "Importantly, high FOXM1 expression level has been correlated with advanced tumor stages, high Gleason score, and poor prognosis." (PMID 32629770, 2020). "Since FOXM1 and KIF20A are consistently over-expressed in docetaxel-resistant PCa cells and tumor tissues, we explored whether FOXM1 contributed to docetaxel resistance by regulating KIF20A transcription and expression." (PMID 33292277, 2020). "Therefore, specific inhibitors like DRI and 9R-201 peptides, FOXM1 Aptamer and TFI-10 that bind to FOXM1 are more effective in reducing tumor growth and activating apoptotic pathways." (PMID 33680951, 2020). "E2A suppresses tumor-initiating capacity by targeting the FoxM1-Wnt/β-catenin pathway." (PMID 31234887, 2019). "FOXM1 is an essential inducer of EMT to promote tumor progression and metastasis." (PMID 31391072, 2019). "Finally, FOXM1 protein expression correlated with a highly similar pattern of aneuploidy clusters and tumor types as seen for FOXM1 mRNA." (PMID 30795624, 2019). "The TF FOXM1 was reported as a core factor involved in the cellular transformation and tumor initiation by regulating the G1/S and G2/M transitions, while the miR-21 could modulate cell proliferation and migration." (PMID 30646895, 2019). "Although previous work has shown that FOXM1 enhances DC maturation in response to house dust mite allergens, it is not known whether FOXM1 affects DC maturation in the context of tumor‐specific immunity." (PMID 30628173, 2019). "As a result, high Fascin expression and high FoxM1 expression in the tumour tissues were both remarkably correlated with worse OS (HR = 4.69, P = 0.002 and HR = 3.95, P = 0.001, respectively) and DFS (HR = 3.92, P = 0.007 and HR = 3.34, P = 0.009, respectively)." (PMID 31783819, 2019). "However, it is still uncertain if FOXM1 isoforms show a differential increase in expression between paired normal and tumor samples." (PMID 30795624, 2019). "Notably, FOXM1 expression was epigenetically regulated by dimethylation on H3 lysine 79 (H3K79me2), a modification present in both tumor cells and BMDCs." (PMID 30628173, 2019). "As FOXM1 was highly expressed in TBM BMDCs, we wondered whether the shorter overall patient survival observed with a high DC infiltration was at least partly due to the high FOXM1 expression in DCs in a tumor environment." (PMID 30628173, 2019). "Accompanying this suppression of tumor growth by NB-73, the expression of FOXM1-regulated genes, including the FOXM1 gene itself, was reduced in tumors in a dose-dependent manner, with all gene expressions being greatly reduced upon treatment with 10 mg/kg NB-73." (PMID 31815181, 2019). "However, a recent study has shown that circ_0061140 exerts tumor-promoting effects by sponging miR-370, which targets FOXM1." (PMID 31829231, 2019). "Combined with previous studies and the results above, targetting FOXM1 could promote the sensitivity of tumor cells to chemotherapy." (PMID 30782607, 2019). "Next, we investigated whether the increased FoxM1 in SW480/shE2A cells can lead to enhanced tumor-initiating capacity." (PMID 31234887, 2019).
tumor (continued). "Therefore, our work indicated that FOXM1 inhibited both maturation of BMDCs and their tumor‐suppressing function while promoting tumorigenesis." (PMID 30628173, 2019). "Overall, increased FOXM1 resulted in accelerated tumor growth." (PMID 30628173, 2019). "Furthermore, we found that HMGA1 and FOXM1 cooperatively promote the tumor angiogenic process in in vitro and in vivo models." (PMID 31311575, 2019). "Interestingly, in our patient cohort we observed a significantly higher expression of FOXM1 in patients who developed a tumor recurrence or responded poorly to chemotherapy when compared with patients with a good clinical outcome." (PMID 31541075, 2019). "Recent work has demonstrated the significance of overexpressed FOXM1 in tumor development." (PMID 30628173, 2019). "High expression of FOXM1 was positively correlated with poor histological grade and advanced tumor–node–metastasis (TNM) stage in HCC; while elevated KIF4A level was positively correlated with vascular invasion, as well as poor histological grade and late TNM stage." (PMID 31072351, 2019). "Here, we have discovered FOXM1 as a novel HMGA1-molecular partner, demonstrating that HMGA1 stabilizes FOXM1 in the nucleus preventing its degradation, increasing FOXM1-dependent transcriptional activity and potentiating its crucial role in tumour angiogenesis." (PMID 31311575, 2019). "Confirmations of the expression degrees of FoxM1 as well as E-cadherin in the nude mouse xenografts were carried out with the help of immunohistochemistry, with brown staining indicating the positive expression of FoxM1, E-cadherin in tumor tissue and blue staining indicating the tumor cell nuclei." (PMID 29313393, 2018). "Using FOXM1 and tumor grade as biomarkers can predict TNBC subtype with 75% accuracy." (PMID 30572639, 2018). "In this study, we synthesized a promising anti-tumor targeted FoxM1 siRNA-loaded cationic nanobubbles (CNBs) conjugated with an A10-3.2 aptamer (siFoxM1-Apt-CNBs), which demonstrate high specificity when binding to prostate-specific membrane antigen (PSMA) positive LNCaP cells." (PMID 29313393, 2018). "FOXM1 exhibits potent oncogenic properties in promoting cell proliferation, chromosome instability, stem cell self-renewal, and functions as activator of tumor metastasis through enhancing epithelial–mesenchymal transition, cell migration, invasion and angiogenesis." (PMID 30486864, 2018). "FoxM1 has been shown to play a role in tumor invasion, migration, and angiogenesis." (PMID 29423068, 2018). "On multivariate analysis using the Cox proportional hazards model, FoxM1 overexpressing cases in late stage demonstrated significant poor survival when adjusted for age, histology, tumor grade and TNBC (hazard ratio, 1.82; 95% confidence interval [95% CI], 1.06-3.37 [p = 0.0298])." (PMID 29707121, 2018). "In summary, we have demonstrated in both in vitro cell cultures and in vivo tumor models of HNSCC that mutant p53s can acquire GOF properties through a transcription independent mechanism promoting FOXM1 expression through inhibition of AMPK-mediated FOXO3a activation." (PMID 29269868, 2018). "It has been reported that exogenous FoxM1 significantly enhances tumor growth." (PMID 29700308, 2018). "In vivo xenografts tumors in nude-mouse model results showed that siFoxM1-Apt-CNBs combined with UMND led to significant inhibition of tumor growth and prolonged the survival of the mice, with low toxicity, an obvious reduction in FoxM1 expression, and a higher apoptosis index." (PMID 29313393, 2018). "Rescue of FOXM1 reversed the effect of miR-6868-5p on tumor angiogenesis." (PMID 30486864, 2018). "In addition, our study correlated the decrease of tumor volume induced by the miRNA-370-3p/TMZ treatment with the decrease in FOXM1 and MGMT (i.e., two targets of miR-370-3p)." (PMID 30497054, 2018).
tumor (continued). "Thiazolidinedione (TZD) inhibits FOXM1 expression through downregulation of Sp1, which may negatively regulate tumor cell growth and promote apoptosis." (PMID 30208972, 2018). "Interestingly, we noted that the miR-370-induced reduction in tumor volume was also correlated with the miR-370-induced reduction in FOXM1 expression." (PMID 30497054, 2018). "Here, we also showed that FoxM1 overexpressing cells formed larger and more tumor spheres." (PMID 30416986, 2018). "In addition, as a downstream component of the WNT signaling pathway, FoxM1 is critical for the transcriptional function of β-catenin in tumor cells." (PMID 30580327, 2018). "Thus, siFoxM1-Apt-CNBs combined with UMND achieved a good therapeutic effect in LNCaP cells and xenografts tumor by silencing the expression of FoxM1." (PMID 29313393, 2018). "We reported that miR-6868-5p suppressed tumor angiogenesis by inhibiting FOXM1." (PMID 30486864, 2018). "High FOXM1 transcript levels correlated with high tumor stage and grade." (PMID 29959570, 2018). "FOXM1 (forkhead box protein M1) is a transcription factor that participates in all stages of tumor development, mainly through the control of cell cycle and proliferation, regulating the expression of genes involved in G1/S and G2/M transition and M phase progression." (PMID 29596365, 2018). "The Forkhead box M1 (FoxM1) transcription factor is an important anti-tumor target." (PMID 29313393, 2018). "Since FOXM1 is known to promote tumor angiogenesis and proved as the direct target of miR-6868-5p, we reasoned that miR-6868-5p may regulate tumor angiogenesis through modulating FOXM1 expression." (PMID 30486864, 2018). "Recent evidences have suggested that FoxM1 could be targeted by several tumor suppressor miRNAs19–22." (PMID 29343703, 2018). "Next, we examined whether the FoxM1-ADAM-17 axis played a key role on tumor growth by downregulating the expression of FoxM1 and ADAM-17." (PMID 29776401, 2018). "NKX2.1 was absent in a majority of FoxM1-ΔN-expressing tumor cells and associated with increased extracellular mucus deposition as shown by Alcian Blue staining." (PMID 29267283, 2017). "We also evaluated whether the correlation between FOXM1 expression and outcome of patients is different between tumor types." (PMID 28427178, 2017). "The TF Forkhead Box M1 (FOXM1) is involved in tumor development, and the adenovirus vector AdFOXM1shRNA, which expresses FOXM1-specific short hairpin RNA, may be used as a therapeutic intervention for the treatment of patients with NPC." (PMID 27765529, 2017). "Since Cath-D plays a crucial role in degradation of extracellular matrix (ECM) and tumor invasion, we further identified whether FOXM1 modulates of Cath-D expression using western blot analysis in SGC7901 and MKN28 cells." (PMID 28978107, 2017). "Thus, knockdown of FOXM1 or AGR2 reduced tumor invasion and inhibited mucinous phenotype of human lung A549 adenocarcinomas in vivo." (PMID 29267283, 2017). "Furthermore, we subcutaneously injected MDA-MB-231 cells harbouring stably integrated inducible FOXM1 knockdown shRNA constructs into nude mice to evaluate their effects on tumour growth." (PMID 28114286, 2017). "In addition, immunohistochemistry revealed a reduction in AURKA, FOXM1 and Nanog staining in Dox-treated tumours, compared with the DMSO-treated controls." (PMID 28114286, 2017). "Meanwhile, considering that several studies reported miR-361-5p to act its function by targeting some other factors, such as Twist1, VEGFA and FOXM1, it remains to be explored whether other targets may contribute to the anti-tumor effect of miR-361-5p." (PMID 29132384, 2017). "FoxM1 regulates the transition from the G1 to S and the G2 to M phase in mitosis, and dysregulated FoxM1 expression results in cell cycle arrest and chromosome mis-segregation in tumor cells." (PMID 28767320, 2017). "FOXM1 and b-catenin were detected both in the cytoplasm and the nucleus of tumor cells." (PMID 28423516, 2017).
tumor (continued). "Moreover, FOXM1 is linked to the induction of epithelial–mesenchymal transition (EMT), a process that renders tumor cells more invasive and aggressive." (PMID 26885609, 2016). "More importantly, the immunity induced by CTP-FoxM1-loaded DCs could significantly inhibit tumor growth and metastasis in HCC-bearing mice, which was more potent than that induced by DCs loaded with FoxM1 or CTP, alone." (PMID 27351282, 2016). "FOXM1 regulates a wide spectrum of tumor progression processes." (PMID 27439614, 2016). "Notably, vaccination with DCs pulsed with CTP-FoxM1 provided more efficient tumor suppression in tumor growth and size compared with other groups vaccinated with DCs pulsed with CTP, FoxM1 or PBS." (PMID 27351282, 2016). "Furthermore, in vivo inhibition of FOXM1 by liposomal siRNA-nanoparticles suppressed growth of MDA-MB-231 TNBC tumor xenografts in orthotopic models." (PMID 26918606, 2016). "Expression of FOXM1-WT cells grew large tumors within five weeks, whereas a significant inhibition of tumor growth was observed in the same mice injected with FOXM1-5KR expression cells, which was consistent with the results showed in the MTT growth curve and crystal violet staining assay." (PMID 27542221, 2016). "Inversely, FoxM1 has been shown to directly reshape the epigenomic landscape of tumor cells." (PMID 26464434, 2016). "In this study, we found that SIRT1 directly binds to and deacetylates FOXM1, and participates in regulating FOXM1 acetylation status during cell cycle and FOXM1 transcriptional activities, indicating that SIRT1 acts as a tumor suppressor in regulating FOXM1 activity." (PMID 27542221, 2016). "More importantly, the immunity induced by DCs loaded with CTP-FoxM1 could significantly inhibit tumor growth and metastasis in HCC-bearing mice, which was more potent than that induced by DCs loaded with FoxM1 or CTP, alone." (PMID 27351282, 2016). "Next, the effect of downregulation of FOXM1 on clonogenic survival of GBM tumor cells was examined." (PMID 27764801, 2016). "Finally, treatment of CRC xenograft tumors in nude mice with combination of Cox-2 and FoxM1 inhibitors inhibited tumor growth significantly via down-regulation of Cox-2 and FoxM1 expression." (PMID 26159723, 2015). "Additionally, in vivo mouse studies were performed to confirm the functional involvement of FOXM1 in EOC tumor formation and progression." (PMID 26299613, 2015). "Moreover,miR-320 regulates the Wnt/β-catenin pathway partly by targeting FOXM1 that promotes the tumor initiation and progression." (PMID 26297223, 2015). "However, some studies demonstrated that FOXM1 promoted tumor metastasis by regulating the expression of MMPs." (PMID 26451068, 2015). "The correlation between FOXM1 expression and the tumor thickness." (PMID 26640950, 2015). "First, to confirm the validity of the FOXM1 antibody and assess protein expression in tumour samples we performed western blot analysis of FOXM1 expression in corresponding tissue types from 3 types of gastrectomy specimens: normal tissue (N), high grade dysplasia (D) and tumour (T)." (PMID 26576650, 2015). "Meanwhile, we found that SW620 cells exhibited the much higher metastatic ability, revealing that FOXM1 overexpression may promote the tumor metastasis." (PMID 25935853, 2015). "Additionally, tumor cells overexpressing FOXM1 are resistant to apoptosis and the premature senescence induced by oxidative stress, which has strong implications for resistance to chemotherapy." (PMID 26640950, 2015). "Pathological overexpression of FOXM1 can induce the malignant proliferation of tumor cells." (PMID 26451068, 2015). "Notably, amongst all tumor types with TCGA data, FOXM1 was most frequently amplified in HGSOC, with ~12% of tumors effected." (PMID 26243836, 2015).